NAT1 (N-acetyltransferase 1)
Diseases named in the same sentence as NAT1 in open-access papers (continued):
Sharing a sentence is not in itself a finding about the gene and the disease.
tumor (continued). "Downregulation of NAT1 correlates with decreased CTL and NK cell infiltration, promoting an immunosuppressive environment characterized by increased TAM and Treg presence, which collectively facilitates tumor progression and metastasis." (PMID 39610918, 2024). "NAT1 overexpression inhibits the PI3K/AKT/mTOR signaling pathway, thereby suppressing the EMT (epithelial-mesenchymal transition) process and glycolytic ability of tumor cells." (PMID 38916406, 2024). "This presents a possible therapeutic intervention for patients with low or absent NAT1 in their tumours." (PMID 35918499, 2022). "Consistent with the previous study, we found that the expressions of NAT1 and NAT2 was significantly reduced in tumor tissues at the mRNA and protein levels, possibly attributable to the highly frequent deep deletion of both genes in COAD, which was confirmed by cBioPortal analysis." (PMID 34322151, 2021). "XBP1-positive and NAT1-negative expression was positively related to larger tumor size (>3 cm) in GBC and AC." (PMID 32793479, 2020). "In this study, we have also demonstrated that immunostaining for NAT1 and TWIST1 may be of help to identify the tumor cells with EMT phenotype." (PMID 30610490, 2019). "In our study, genes, such as GATA3, ERBB4, RET, NAT1, and TFF3, typically more expressed in ER positive tumor samples, were also more expressed in stromal cells from ER positive as compared with ER negative tumors (defined by immunohistochemistry of malignant cells)." (PMID 31817155, 2019). "For example, FOXA1, MLPH, NAT1, MAPT and BAG1 are expressed in luminal tumours according to published mRNA profiles and also co-clustered in our data, with higher expression levels in most ERPR tumours." (PMID 26725330, 2016). "Therefore, it should be important to consider NAT1 and MELK genes and their products as the targets in the therapeutic plans for LGG and HGG tumor separately." (PMID 26474389, 2015). "We extracted total RNA from the tumor tissue and quantified human NAT1 mRNA using specific primers that did not amplify the mouse NAT homolog." (PMID 21347396, 2011). "Of interest, six proteins (FOXA1, ERBB2, MAPT, NAT1, PHGDH, KRT5) and one protein (PHGDH) overlapped between PAM50 and the differentially expressed proteins between basal-like and luminal-like subtypes in microdissected tumor epithelium and stroma, respectively." (PMID 37349288, 2023). "Similarly, XBP1-positive expression and NAT1-negative expression were closely related to poorly differentiated type, larger tumor mass, advanced TNM stage (III + IV), lymph node metastasis, invasion, and only receiving biopsy in AC (all P < 0.05)." (PMID 32793479, 2020). "Additionally, the increased SEPT9 methylation seen in NAT1 samples and in stromal cells of tumor tissue does not seem to be reflected in a corresponding reduction in protein levels in the same samples." (PMID 23988185, 2013). "We found that negative NAT1 expression was positively correlated with several malignant clinicopathological parameters of GBC, including poorly differentiated type, larger tumor size (>3 cm), lymph node metastasis, invasion, advanced TNM stage, which is consistent with other reports." (PMID 32793479, 2020).
infection (2 papers, 2018 to 2019). The state of being infected such as from the introduction of a foreign agent such as serum, vaccine, antigenic substance or organism. "In contrast, our study showed that NAT1 is not necessary for either infection or mycotoxin production in the wheat cultivars tested." (PMID 31299046, 2019). "NAT1 deletion did not affect infection severity among fifteen wheat cultivars grown the Northwestern region." (PMID 31299046, 2019). "Moreover, the viral miRNA miR-BART1-3p plays a role in anti-apoptosis, and may hijack the acetylation function of NAT1 by repressing the NAT1 gene, so that EBV exploits other acetyltransferases to perform the acetylation at both infection stages." (PMID 30133498, 2018).
neurodegenerative disease (1 paper, 2024). A disorder of the central nervous system characterized by gradual and progressive loss of neural tissue and neurologic function. "The NAT-1 therefore constitutes a pertinent tool for investigating brain activity in, e.g., drug discovery and models of neuropsychiatric and/or neurodegenerative diseases with minimal effects on pharmacological and behavioural outcomes." (PMID 39199395, 2024).
NAT1 also shares sentences with these, for which no sentence is quoted: adenocarcinoma (2 papers); adenoma (1); adult-onset Still disease (1); autism (1); brain cancer (1); breast (1); candidiasis (1); colorectal adenoma (1); endometriosis (1); epilepsy (1); gastric carcinoma (1); Hypertension (1); inflammatory bowel disease (1); insomnia (1); keratosis (1); laryngeal carcinoma (1); membranous nephropathy (1); mental disorder (1); metabolic disorder (1); metastatic colorectal cancer (1); metastatic disease (1); neuroblastoma (1); non-Hodgkin lymphoma (1); Obesity (1); oesophageal adenocarcinoma (1); personality disorder (1); prostate tumors (1); pulmonary disorder (1); rectum adenocarcinoma (1); respiratory disease (1).
A further 2 diseases each share a sentence with NAT1 in 1 paper.